MUC4 (mucin 4, cell surface associated)
Diseases named in the same sentence as MUC4 in open-access papers (continued):
Sharing a sentence is not in itself a finding about the gene and the disease.
adenoma (5 papers, 2016 to 2025). A neoplasm arising from the epithelium. "In our study, loss of Muc4 in AMC mice resulted in severe rectal bleeding with more adenomas in the colon and rectal regions." (PMID 35255004, 2022). "In contrast, expression of MUC4 was significantly downregulated during adenoma and adenocarcinoma progression in CRC tissues as evident from human microarray analyses." (PMID 35255004, 2022). "A recent study from our lab corroborated these findings via the immunohistochemistry of premalignant and malignant tissues, which showed MUC4 was significantly reduced in the adenoma-carcinoma sequence relative to normal tissue." (PMID 27551331, 2016). "Importantly, mucins in Smad4Δ/Δ adenomas were among the DEGs with Muc4, Muc20, Muc2 being upregulated and Muc6 being downregulated (padj p < 0.05)." (PMID 40348815, 2025). "In one study, serrated adenomas displayed a complete loss of MUC4 expression while 50% of hyperplastic polyps showed reduced MUC4 expression and traditional adenomas (flat or sessile adenomas and polypoid adenomas) showed no change in MUC4 expression compared to normal." (PMID 27551331, 2016). "We previously reported that the transmembrane mucin MUC4 is aberrantly expressed in different cancers, though its expression in CRC was lost in the adenoma-carcinoma sequence." (PMID 32098629, 2020).
gallbladder carcinoma (5 papers, 2008 to 2023). "This study revealed for the first time that MUC4 expression in gallbladder carcinoma is an independent risk factor for poor outcome." (PMID 23101681, 2012). "In gallbladder carcinoma, high MUC4 expression was significantly associated with poor survival." (PMID 37324940, 2023). "To date, the relation between MUC4 expression and prognosis in gallbladder carcinoma remains to be determined." (PMID 23101681, 2012). "For gallbladder carcinoma, positive staining of MUC4, MUC1, and MUC2 was 55.6%, 81.0%, 28.6%, respectively." (PMID 23101681, 2012). "This study shows that MUC4 expression is an independent poor prognostic factor in gallbladder carcinoma." (PMID 23101681, 2012). "However, little information is known about the prognostic role of MUC4 in gallbladder carcinoma, although gallbladder carcinoma is the most common malignancy in the biliary tract." (PMID 23101681, 2012). "Authors examined MUC4 expression in gallbladder carcinoma and investigated its impact on prognosis." (PMID 23101681, 2012). "MUC4 expression in gallbladder carcinoma is an independent poor prognostic factor." (PMID 23101681, 2012). "Therefore, MUC4 expression may be a useful marker to predict the outcome of patients with surgically resected gallbladder carcinoma." (PMID 23101681, 2012). "Therefore, authors investigated MUC4 expression in gallbladder carcinoma by immunohistochemical staining to determine whether MUC4 expression could be a potential prognostic factor for gallbladder carcinoma." (PMID 23101681, 2012). "The expression profiles of MUC4, MUC1, MUC2 mucins in gallbladder carcinoma tissues from 63 patients were investigated using immunohistochemical staining." (PMID 23101681, 2012). "However, there has been no report on the prognostic role of MUC4 expression in gallbladder carcinoma." (PMID 23101681, 2012).
gastric tumors (5 papers, 2018 to 2025). "In a previous study with 63% Hp positivity, Hp was significantly positively associated with the expression of the intestinal mucins MUC2 and MUC4 in gastric tumors." (PMID 37674528, 2023). "Although the MUC4-positive gastric tumor was diagnosed as sclerosing epithelioid fibrosarcoma (SEF), the depicted histology suggests similarity to the current cases with variable clear cell epithelioid pattern, lacking characteristic sclerosis of SEF." (PMID 34228212, 2022). "Previous studies observed MUC4 in human gastric tumors but did not examine cell type–specific expression." (PMID 37674528, 2023).
head and neck cancer (5 papers, 2017 to 2022). A primary or metastatic malignant neoplasm affecting the head and neck. "MUC4 is selective tumor antigen of pancreatic, ovarian and head and neck carcinoma MUC4 vaccines are investigated as novel anticancer therapies." (PMID 36700235, 2022). "With regard to UICC stage, elevated MUC4 expression was referred to play a worse prognostic role in head and neck cancers (n = 1, RR = 0.56, 95% CI: 0.39-0.80, p = 0.002) than MUC1 (n = 9, RR = 0.87, 95% CI: 0.76-1.00, p = 0.052)." (PMID 29221212, 2017).
non-small cell lung carcinoma (5 papers, 2014 to 2022). A group of at least three distinct histological types of lung cancer, including non-small cell squamous cell carcinoma, adenocarcinoma, and large cell carcinoma. "Among 23 co-occurred pairs which we detected in our current AA ESCC tumor samples, mutant MUC4 and MUC12 pairing is interesting as this pair was previously observed in smoking-associated non-small cell lung cancer patients." (PMID 34285259, 2021). "We correlated the mutation frequency of MUC4, MUC6, and MUC12 with the non-small-cell lung carcinoma, and identified a distinct mutation frequency in tumor samples from smokers (20%) and non-smokers (6%), which cumulatively designates these MUC genes as diagnostic and prognostic markers in smokers." (PMID 24947164, 2014).
triple-negative breast carcinoma (5 papers, 2018 to 2023). An invasive breast carcinoma which is negative for expression of estrogen receptor (ER), progesterone receptor (PR), and human epidermal growth factor receptor 2 (HER2). "This is partly explained by the higher number of triple-negative breast cancer (TNBC) cases in the Hungarian cohort, where, in four out of six cases, a mutation was detected in the MUC4 gene." (PMID 37239898, 2023). "Mucin 4 (MUC4), a potential oncogene with a RARE, inducible by RA, and associated with triple-negative breast cancer, is significantly induced by ALDH1A3 and RA in MDA-MB-231 cells, but not in MDA-MB-468 cells." (PMID 31590252, 2019).
tubular adenoma (5 papers, 2016 to 2023). A usually polypoid neoplasm arising from the glandular epithelium. "Furthermore, IHC staining of mouse tubular adenomas suggested that MUC4 loss is associated with increased cytosolic/nuclear β-catenin." (PMID 27551331, 2016). "In another study, hyperplastic polyps had a reduction in MUC4 expression, while tubular adenoma samples showed normal levels of MUC4 in the same study." (PMID 35255004, 2022). "Based on the immunohistochemistry, staining of MUC4 was observed in precursor lesions of CRC and it was reduced in serrated adenoma and in 50% of HP, whereas tubular adenoma (TA) had normal levels of MUC4." (PMID 32168759, 2020). "No change in the expression of tubular adenomas was seen compared to normal tissue, while serrated adenomas showed a complete loss of MUC4." (PMID 36900282, 2023). "Expression of colonic mucins (MUC1, MUC4, MUC17, MUC2, and MUC5AC) and O-glycans [Sialyl LewisA (CA19-9) and Tn/Sialyl-Tn on MUC1] were analyzed in HP (n=33), SSA/P (n=39), and tubular adenoma (TA) (n=36) samples by immunohistochemistry." (PMID 27705923, 2017).
Crohn disease (4 papers, 2014 to 2024). A gastrointestinal disorder characterized by chronic inflammation involving all layers of the intestinal wall, noncaseating granulomas affecting the intestinal wall and regional lymph nodes, and transmural fibrosis. "(F) Dot plot showing that the expression of MUC4 was higher in four cell types of human inflamed colon with Crohn’s disease." (PMID 37855835, 2023). "Mucins including MUC4, MUC12 and MUC17 are important for intestinal integrity and have previously been associated with both ulcerative colitis (UC) and Crohn's disease (CD)." (PMID 24988487, 2014). "Reduced expression levels of several mucin genes, including MUC3, MUC4, and MUC5B in patients with Crohn’s disease, suggest primary or early mucosal defect of these genes." (PMID 35038288, 2022). "When examining gene expression of 130 known epithelial integrity genes we found no apparent trends toward altered expression in patients with controlled Crohn’s disease relative to controls including MUC1 and MUC4 which have previously been shown to remain dysregulated in controlled Crohn’s disease." (PMID 38830904, 2024).
esophageal cancer (4 papers, 2018 to 2023). A primary or metastatic malignant neoplasm involving the esophagus. "The detection of CNV and mutations of the Muc4 gene may be used as an ultra-early screening indicator for esophageal cancer." (PMID 36430789, 2022). "Therefore, novel assays must be developed for clinical application before MUC4 could be used as a possible diagnostic biomarker of oesophageal cancer." (PMID 37958425, 2023). "Combined with the mutation data of human esophageal cancer in our in-house data, we found that Muc4 mutation in human tissue samples also started to appear at the stage of ESSH, which suggests that Muc4 may play an important role in the early screening of ESCC." (PMID 36430789, 2022). "Furthermore, we identified that missense mutations of Muc4 occurred at all stages, which might be an important molecular locus in the carcinogenesis of mouse esophageal cancer." (PMID 36430789, 2022). "In summary, these data indicate correlation between the proproliferation and antiapoptotic effects of MUC13 with the expression of GLANT14, MUC3A, MUC1, MUC12 and MUC4 in esophageal cancer." (PMID 37395858, 2023). "In this study, we confirmed that GLANT14, MUC3A, MUC1, MUC12, and MUC4 regulatory factors which related to the O-glycan process were overexpressed and downregulated with MUC13 knockdown in esophageal cancer cells, resulting in insufficient tumor growth and proliferation." (PMID 37395858, 2023).
glioblastoma (4 papers, 2020 to 2023). The most malignant astrocytic tumor (WHO grade IV). "We therefore evaluate the clinical relevance of EGFR, MMP9, and MUC4 proteins for glioblastoma diagnosis and prognosis." (PMID 36400876, 2022). "Moreover, MUC4 is co-expressed with MMP9 and EGFR in the proliferative microvasculature of glioblastoma, suggesting a potential role for MUC4 in microvascular proliferation and angiogenesis." (PMID 36400876, 2022). "In conclusion, MMP9 and MUC4 are both expressed in the microvasculature of glioblastoma, indicating both proteins may be involved in angiogenesis and microvascular proliferation (MVP)." (PMID 36400876, 2022). "Overexpression of MUC4, a highly O-glycosylated protein, was observed in glioblastoma (GBM) cell lines and may take part in processes that promote GBM cell invasion and proliferation through upregulation of epidermal growth factor receptor (EGFR)." (PMID 37231524, 2023). "For example, MUC4 has been shown to be involved in cell proliferation and invasion by upregulation of EGFR in glioblastoma cells." (PMID 32604718, 2020). "Finally, MMP9 mean protein level was significantly higher in the serum of glioblastoma compared with grade III glioma patients, whereas MUC4 mean protein level was minimally elevated in higher glioma grades (III and IV) compared with control." (PMID 36400876, 2022). "Our results suggest that MUC4, along with MMP9, might account for glioblastoma progression, representing potential therapeutic targets, and suggesting the ‘MUC4/MMP9/EGFR axis’ may play a vital role in glioblastoma diagnostics." (PMID 36400876, 2022).
glioma (4 papers, 2020 to 2024). A benign or malignant brain and spinal cord tumor that arises from glial cells (astrocytes, oligodendrocytes, ependymal cells). "Given that MMP9 has been proposed as a prognostic and diagnostic marker in glioma, our observations that MUC4 was at least as efficient as MMP9 in discrimination between grades indicates it may act as a biomarker in glioma diagnosis." (PMID 36400876, 2022). "Protein expression in patients with grade II-IV gliomas demonstrated that MUC4 is significantly upregulated during glioma progression, leading to the potential for a role in proliferation and angiogenesis." (PMID 39767713, 2024). "Specific mucins that have now been implicated in glioma include MUC1, MUC4, MUC15, MUC16, MUC17, MUC18 and MUC21." (PMID 39767713, 2024). "They include P2Y14 receptor protein, SIRPα1, and MUC4, which are overexpressed in glioma cells and eventually produce biological effects such as glioma cell proliferation, invasion, and adhesion." (PMID 37231524, 2023). "Our results showed that albeit MUC4 levels were low, they were only minimally elevated in higher glioma grades (III and IV) compared to controls, although the difference was not significant, which needs confirmation in a larger cohort of patients." (PMID 36400876, 2022). "EGFR, MMP9, and MUC4 expression levels were assessed in FFPE tissue biopsies from 60 glioma patients (20 grade II, 20 grade III, and 20 GBM patients, following the 2016 WHO classification)." (PMID 36400876, 2022). "We further investigated the potential use of MMP9 and MUC4 proteins as serum biomarkers in glioma patients." (PMID 36400876, 2022). "In addition to being expressed in the microvasculature, our results showed that MUC4 total expression increases during glioma progression, with higher protein expression in GBM compared to lower grades (grades II and III)." (PMID 36400876, 2022). "Overall, this could suggest that, like MMP9, MUC4 could be involved in glioma progression as well as in angiogenesis/microvascular proliferation in GBM and could serve as a potential therapeutic target." (PMID 36400876, 2022). "MMP9 and MUC4 tissue protein expression were significantly correlated with glioma grades." (PMID 36400876, 2022). "However, to the best of our knowledge, the association between MUC4 and glioma progression in clinical samples has not been studied so far." (PMID 36400876, 2022). "In addition, the strong correlation of MUC4 and MMP9 expression with clinicopathological stage suggests both could serve as useful tissue diagnostic biomarkers in glioma patients." (PMID 36400876, 2022). "Based on the current literature, expression profiles, and biological properties, MUC1, MUC4, MUC16, and MUC18 are of interest as precision biomarkers in glioma." (PMID 39767713, 2024). "Immunohistochemistry (IHC) and immunofluorescence (IF) in fixed tissue samples of glioma patients were used to evaluate the expression and localization of EGFR, MMP9, and MUC4." (PMID 36400876, 2022). "Overall, our study postulates a disturbance in the EGFR/MUC4/MMP9 signalling axis as a potential novel and rationalized biomarker panel for glioma." (PMID 36400876, 2022). "As already indicated, MUC4 and MMP9 can be detected and measured in tissue biopsies systematically collected in patients diagnosed with glioma." (PMID 36400876, 2022). "In this study, the role of MUC4, MMP9, and EGFR in the progression and clinical outcome of glioma patients was investigated." (PMID 36400876, 2022). "We demonstrated that MUC4 and MMP9 are both significantly upregulated during glioma progression." (PMID 36400876, 2022). "In general, EGFR interacts with members of the mucin family in cancer, and as such, MUC4 may physically interact with EGFR in a ligand-dependent manner, leading to downstream signalling and MMP9-mediated glioma initiation and progression." (PMID 36400876, 2022).
glioma (continued). "The results showed that when used individually, MMP9 and MUC4 tissue expression can predict clinical outcome in glioma patient diagnosis, which is not the case with EGFR." (PMID 36400876, 2022). "MUC4 appears to be a central player in mucin interaction, with experimental data connecting it to nearly every other mucin, despite no direct specificity for glioma." (PMID 39767713, 2024). "MMP9 and MUC4, but not EGFR, protein expression is correlated with increased glioma histological grades and IDH-WT genotype." (PMID 36400876, 2022). "The MUC4/MMP9/EGFR combined low expression significantly predicted better survival in glioma patients in comparison with the ‘double high’ group and the difference was again more significant than the previous analysis that combined MMP9 and MUC4 only (without EGFR) (p = 0.004, Log-rank)." (PMID 36400876, 2022). "Finally, we explored the potential of MUC4 and MMP9 as serum biomarkers by measuring protein levels in serum samples of high-grade glioma patients and non-glioma (control) individuals." (PMID 36400876, 2022).
head and neck squamous cell carcinoma (4 papers, 2018 to 2023). A squamous cell carcinoma that arises from any of the following anatomic sites: lip and oral cavity, nasal cavity, paranasal sinuses, pharynx, larynx, and salivary glands. "DNA alterations in KMT2C and MUC4 have been observed in the somatic tissue of medulloblastoma and head and neck squamous cell carcinoma patients, respectively." (PMID 32508881, 2020).
intrahepatic cholangiocarcinoma (4 papers, 2009 to 2023). A carcinoma that arises from the intrahepatic bile duct epithelium in any site of the intrahepatic biliary tree. "MUC4 is a novel prognostic factor of intrahepatic cholangiocarcinoma." (PMID 36817485, 2023).
kidney cancer (4 papers, 2018 to 2024). Primary or metastatic malignant neoplasm involving the kidney. "Among these, MUC4 has been reported to be associated with exophytic growth of clear cell renal cell carcinoma while VHL linked to a primary oncogenic driver in kidney cancers." (PMID 32714868, 2020). "The enrichment of mutation of MUC4 could be related with the fact that the first risk factor of kidney cancer is smoking and that kidney cancer diagnosis is occurring at elder ages (65 years)." (PMID 30236127, 2018). "Of interest, MUC4 was upregulated in two datasets while it was downregulated in four datasets in kidney cancer." (PMID 34336844, 2021). "Regarding somatic mutations, VHL has the highest prevalence (43.2%) in the entire population considered from the kidney cancer TCGA dataset (N = 424), followed by PBRM1 and MUC4, both slightly above 20%." (PMID 39199616, 2024).
lymphoma (4 papers, 2021 to 2025). A malignant (clonal) proliferation of B- lymphocytes or T- lymphocytes which involves the lymph nodes, bone marrow and/or extranodal sites. "Seven gene mutations (Ankrd11, C130026I21 Rik, Gm10717, Gm10721, Gm11168, Muc4, and Zfp984) were hetero-/hemi-zygous in all three lymphomas and one gene (Itgav) had homozygous mutations in one lymphoma." (PMID 37145994, 2023). "WES revealed significantly mutated genes, including several known (NCF1, MMP9, and VDR) and possibly other candidate (CNN2, MUC4, MTSS2, KMT2C, HAVCR2, and TCF19) genes, most of which were associated with the physiological activation of lymphoma cells." (PMID 41296384, 2025).